TNPO3 (transportin 3)
Description:
Importin, which transports target proteins into the nucleus. Specifically mediates the nuclear import of splicing factor serine/arginine (SR) proteins, such as RBM4, SFRS1 and SFRS2, by recognizing phosphorylated SR domains. Also mediates the nuclear import of serine/arginine (SR) protein CPSF6, independently of CPSF6 phosphorylation. The nuclear import process is regulated by the small GTPase Ran that partitions between cytoplasm and nucleus in the predominantly GDP- and GTP-bound form, respectively. Importin associates with target cargo proteins in the cytoplasm, and the competitive binding of GTP-bound Ran induces the release of cargos in the nucleus. (Microbial infection) Involved in immunodeficiency virus (HIV-1) infection by importing the pre-integration complex (PIC) into the nucleus. Required for a nuclear maturation step of HIV-1 prior to integration.
Synonyms: TRN-SR; IPO12; MTR10A; TRN-SR2; LGMD1F; LGMDD2; TRNSR
Tractability: Small molecule: a structure with a bound ligand is known. PROTAC: ubiquitination databases record sites on it; its protein half-life has been measured.
Target class: Transporter
Gene: Protein-coding gene on chromosome 7 (128,954,180 to 129,055,173, reverse strand). Ensembl gene ENSG00000064419.
Subcellular location: Nucleus envelope; Cytoplasm
Subcellular location (Human Protein Atlas): Cytosol; Nucleoplasm
Gene Ontology:
Molecular function: identical protein binding; protein binding; small GTPase binding; nuclear import signal receptor activity
Biological process: protein import into nucleus
Cellular component: annulate lamellae; cytoplasm; cytosol; nuclear envelope; nucleoplasm
Genetic constraint (gnomAD): Loss-of-function variants: 57 observed, 108.59 expected, observed/expected ratio (o/e) 0.52, 90% interval 0.42 to 0.65. The upper end of that interval is the gene's LOEUF score, 0.65, which puts it in group 2 of 6, group 1 being the genes least tolerant of losing a copy. Missense variants: 763 observed, 1,069.9 expected, observed/expected ratio (o/e) 0.71, 90% interval 0.67 to 0.76. Synonymous variants: 334 observed, 394.42 expected, observed/expected ratio (o/e) 0.85, 90% interval 0.77 to 0.93.
Gene-disease validity (ClinGen):
ClinGen rates the evidence that TNPO3 causes each of these diseases.
muscular dystrophy, limb-girdle, autosomal dominant (autosomal dominant): Definitive.
Homologues: Orthologues: chimpanzee TNPO3 (100% identical), macaque TNPO3 (100% identical), dog TNPO3 (99% identical), pig TNPO3 (99% identical), mouse Tnpo3 (99% identical), rabbit TNPO3 (99% identical), guinea pig TNPO3 (99% identical), rat Tnpo3 (99% identical), tropical clawed frog tnpo3 (88% identical), zebrafish tnpo3 (86% identical), Drosophila melanogaster Tnpo-SR (43% identical), Caenorhabditis elegans tsr-1 (26% identical). Paralogues in human: IPO13 (24% identical).
Diseases named in the same sentence as TNPO3 in open-access papers:
TNPO3 is named in the same sentence as 38 diseases in open-access papers, as found by Europe PMC text mining. Sharing a sentence is not in itself a finding about the gene and the disease. The quoted sentences say what the papers report.
HIV-1 infection (27 papers, 2008 to 2024). The type species of lentivirus and the etiologic agent of acquired immunodeficiency syndrome (AIDS). "Our data revealed that the mutation of TNPO3 present in patients with LGMD1F protected PBMCs from HIV-1 infection." (PMID 31465518, 2019). "Our results demonstrate that cells from patients with this mutation in TNPO3 are resistant to HIV-1 infection in vitro." (PMID 31465518, 2019). "Altogether, these results imply that the effect of TNPO3-depletion on HIV-1 infection is in part linked to CPSF6." (PMID 22888429, 2012). "These patients have a mutation in the TNPO3 gene that makes them resistant to HIV-1 infection." (PMID 34204384, 2021). "Besides this role in HIV-1 infection, TNPO3 is also linked to a rare muscular dystrophy termed LGMD1F." (PMID 31465518, 2019). "Moreover, PBMCs from all patients showed similar resistance to HIV-1 infection, while there is a wide variability in the muscular clinical symptoms that affects these patients, although all of them share the same TNPO3 mutation." (PMID 31465518, 2019). "In contrast, CsA had minor effects on WT HIV-1 infection in either control cells or TNPO3-knockdown cells." (PMID 37355754, 2023). "Because TNPO3 is a common factor in both HIV-1 infection and LGMDD2 disease progression, our group has previously studied the susceptibility to in vitro HIV-1 infection in T cells isolated from LGMDD2 patients." (PMID 35646913, 2022). "The mechanism behind this resistance to HIV-1 infection was due to a strong decrease in HIV-1 integration probably related to the defective transport of CPSF6 by TNPO3 and the formation of TNPO3-CPSF6-capsid complexes." (PMID 35646913, 2022). "Further genome wide siRNA screening and a subsequent yeast two-hybrid screening identified transportin 3 (TNPO3) as a host co-factor for HIV-1 infection." (PMID 34204384, 2021). "A single substitution in HIV-1 CA, N74D, can bypass CPSF6 binding and relieve the inhibitory effects of TNPO3 depletion on HIV-1 infection (9, 13, –, 15)." (PMID 34154414, 2021). "Among these cellular proteins, nucleoporins (NUPs), cleavage and polyadenylation specificity factor 6 (CPSF6), as well as the β-karyopherin transportin-SR2 (TRN-SR2; transportin-3), have been proposed to support HIV-1 infection." (PMID 34612665, 2021). "TNPO3 has been involved in the nuclear transport of serine/arginine-rich proteins such as splicing factors and also in HIV-1 infection through interaction with the viral integrase and capsid." (PMID 31465518, 2019). "Back-complementation with the mutant form of the protein (TNPO3 shRNA+TNPO3_mut) resulted in lower recovery of HIV-1 infection." (PMID 31465518, 2019). "Some studies suggest that TNPO3 participates in the nuclear import of PICs whereas other authors propose that TNPO3 promotes HIV-1 infection though the interaction with HIV-1 CA or indirectly through the interaction of CPSF6 with HIV-1 CA." (PMID 31465518, 2019). "Being TNPO3 a co-factor of HIV-1 replication, the susceptibility to HIV-1 infection of peripheral blood mononuclear cells (PBMCs) isolated from LGMD1F patients was analyzed." (PMID 31465518, 2019). "More recent studies indicate that the effect of TNPO3 depletion on HIV-1 infection is mediated by redistribution of the SR protein CPSF6 from the nucleus to the cytoplasm." (PMID 30084827, 2018). "Among these host molecules, transportin 3 (TNPO3), RanBP2 and Nup153 are of particular interest for the following reasons: 1) Knockdown of these molecules blocks HIV-1 infection after reverse transcription but before integration." (PMID 24415937, 2014). "Expression of CPSF6 is required for the HIV-1 infection phenotype observed in human TNPO3-depleted cells." (PMID 25496772, 2014). "To understand the role of CPSF6 in the ability of TNPO3-depleted HeLa cells to inhibit HIV-1 infection, we measured HIV-1 infectivity in HeLa cells simultaneously silenced for the expression of TNPO3 and CPSF6." (PMID 23622145, 2013).
HIV-1 infection (continued). "Because depletion of TNPO3 prevents HIV-1 infection after nuclear import, we studied the formation of 2-LTR circles blocking the enzymatic activity of HIV-1 integrase by genetic or pharmacological means." (PMID 23622145, 2013). "Since the identification of TNPO3 as a factor required for HIV-1 infection many studies have attempted to understand the specific function of this karyopherin in viral replication." (PMID 23414560, 2013). "In agreement with previous observations, we found that TNPO3-depleted cells inhibit HIV-1 infection after nuclear import, as suggested by the presence of 2-LTR circles." (PMID 23622145, 2013). "This work explores the role of cleavage and polyadenylation specificity factor subunit 6 (CPSF6) in the ability of TNPO3-depleted cells to inhibit HIV-1 infection." (PMID 23622145, 2013). "This work tested the role of CPSF6 in the ability of TNPO3-depleted cells to inhibit HIV-1 infection." (PMID 23622145, 2013). "To explore the role of TNPO3 during HIV-1 infection, we challenged shRNA control and TNPO3 K.D. cells with HIV-1 and HIV-1-N74D to measure the formation of 2-LTR circles and productive infection 24 and 48 hours post-infection, respectively." (PMID 23622145, 2013). "Overall, these experiments indicated that CPSF6 is required for the ability of TNPO3-depleted cells to inhibit HIV-1 infection." (PMID 23622145, 2013). "There is some evidence to suggest that the primary function of TNPO3 during HIV-1 infection is control of CPSF6 localization within the cell." (PMID 24103892, 2013). "Our siRNA depletion experiments showed that CPSF6 is necessary for the ability of TNPO3-depleted cells to inhibit HIV-1 infection." (PMID 23622145, 2013). "Studies on the formation of 2-LRT circles during HIV-1 infection revealed that TNPO3-depleted cells are impaired in the integration process or exhibit a defect in the formation of 2-LTR circles." (PMID 23622145, 2013). "Depletion of TNPO3 expression in mammalian cells inhibits HIV-1 infection after reverse transcription but prior to integration." (PMID 23622145, 2013). "Remarkably, the Fassati group demonstrated that more capsid accumulates in the nucleus of TNPO3-depleted cells during HIV-1 infection relative to wild-type cells." (PMID 22888429, 2012). "Altogether, this evidence points out capsid as an important determinant for the requirement of TNPO3 during productive HIV-1 infection." (PMID 22888429, 2012). "In contrast to integrase, genetic and biochemical evidence exists for capsid as a determinant for the requirement of TNPO3 during HIV-1 infection." (PMID 22888429, 2012). "A C-terminal truncated form of CPSF6 (CPSF6-358) inhibits HIV-1 infection and the TNPO3-independent CA mutant viruses N74D, Q63A/Q67A and E45A are resistant to CPSF6-358 restriction." (PMID 22145813, 2011). "Further characterization of the crosstalk between HIV-1 infection and LGMDD2 disease may contribute to a better understanding of both the cellular alterations occurring in LGMDD2 patients and the role of TNPO3 in the HIV-1 cycle." (PMID 35646913, 2022). "Expression of the cellular karyopherin TNPO3/transportin-SR2/Tnp3 is necessary for HIV-1 infection." (PMID 23622145, 2013). "Instead, TNPO3 promotes HIV-1 infection indirectly, by inhibiting an inhibitor of HIV-1, CSPF6." (PMID 23414560, 2013). "While IN may engage TNPO3 in the context of HIV-1 infection, the potential role for this interaction in PIC nuclear localization appears auxiliary to that played by CA." (PMID 24103892, 2013). "Because TNPO3-depleted cells inhibit HIV-1 infection in a CPSF6-dependent manner, we tested whether TNPO3-depleted cells inhibit HIV-1 infection by the mechanism used by CPSF6-358." (PMID 23622145, 2013). "As previously shown depletion of TNPO3 blocks HIV-1 infection after nuclear import." (PMID 23622145, 2013).
HIV-1 infection (continued). "Similar profiles were observed in infected cells (data not shown), indicating that HIV-1 infection does not trigger major changes in the distribution of LEDGF/p75 or TNPO3-associated complexes." (PMID 23369367, 2013). "To shed light on the mechanism by which TNPO3 contributes to HIV-1 infection we engineered a panel of twenty-seven single-cycle HIV-1 vectors each bearing a different CA mutation and characterized them for the ability to transduce cells in which TNPO3 had been knocked down (KD)." (PMID 22145813, 2011). "In addition, the viral determinant for the requirement of TNPO3 in HIV-1 infection is discussed." (PMID 22888429, 2012). "More recent experiments with this same in vitro assay have provided evidence that certain tRNAs may also promote RTC import, and the role of another importin in HIV-1 infection, Transportin 3, has been reported, further implicating multiple pathways in this process." (PMID 18687138, 2008). "Cellular depletion of TNPO3 or truncation of the RS domain mislocalized CPSF6 to the cytoplasm and potently restricted HIV-1 infection." (PMID 34154414, 2021). "In contrast, HIV-1 infection in HeLa cells exhibited a marked requirement for specific nucleoporins, particularly NUP358 and NUP153 and the transport receptor TNPO3, in agreement with previous observations." (PMID 30496303, 2018). "A number of phenotypic similarities suggest the roles of TNPO3, NUP153, NUP358, CPSF6, and CypA during HIV-1 infection are interrelated." (PMID 24103892, 2013). "At least for TNPO3, NUP358, and NUP153, such concerns are somewhat assuaged by subsequent findings which demonstrated that the knockdowns affected HIV-1 infection in relatively specific, CA-dependent manners." (PMID 24103892, 2013). "The functions of these nuclear transport factors and NPC proteins in HIV-1 infection have yet to be defined, although HIV-1 infectivity is clearly reduced upon depletion of Nup358 and TNPO3." (PMID 23959328, 2013). "Depletion of TNPO3 and CPSF6 completely rescues HIV-1 infection when compared to TNPO3 K.D. HeLa cells transfected with a non-target siRNA." (PMID 23622145, 2013). "Our findings showed that depletion of TNPO3 expression inhibits HIV-1 infection, while the simultaneous depletion of TNPO3 and CPSF6 expression rescues HIV-1 infection." (PMID 23622145, 2013). "Differently from TNPO3-depleted cells, overexpression of cytosolic full-length CPSF6 inhibited HIV-1 infection before nuclear import." (PMID 23622145, 2013). "Interestingly, Matreyek and Engelman have reported that co-depletion of Nup153 and TNPO3 yielded synergistic inhibitory effects on HIV-1 infection, underscoring the fact that simultaneous targeting of multiple HDFs might be a potentially useful therapeutic/preventive approach." (PMID 23028330, 2012). "However, TNPO3 is also responsible for the nuclear import of CPSF6 which, in HIV-1 infection, favors nuclear transport." (PMID 33868211, 2021). "Of note, nuclear transport has not been widely studied as a potential target to HIV-1 infection and only recently new hits impeding TNPO3-IN interactions blocking HIV-1 nuclear transport have been described." (PMID 31465518, 2019). "Due to the central role of TNPO3 in HIV-1 nuclear import, we hypothesized that HIV-1 infection might be impaired in PBMCs from LGMD1F patients." (PMID 31465518, 2019). "However, the inherent dependence of HIV-1 infection upon NUP358, NUP153 and TNPO3 in HeLa cells confounds this analysis since their depletion results in less efficient infection regardless of MX2 expression." (PMID 30496303, 2018). "We observed several CA-dependent, cell cycle-dependent, and cell-type dependent differences in sensitivity to TNPO3 and/or CPSF6 depletion that suggested additional cellular factors may influence their effect on HIV-1 infection." (PMID 30084827, 2018).
HIV-1 infection (continued). "Engagement of CPSF6 is not required for HIV-1 infection in transformed cell lines but is tightly correlated with dependence on the nuclear entry cofactors TNPO3, NUP153 and NUP358." (PMID 25356722, 2014). "To understand whether the cytosolic fraction of CPSF6 is responsible for the inhibition of HIV-1 in TNPO3-depleted cells, we tested the ability of a cytosolic full-length CPSF6 to block HIV-1 infection." (PMID 23622145, 2013). "The fact that HIV-1-N74D is insensitive to TNPO3-depletion and overcomes the restriction imposed by a fragment derived from CPSF6 suggests a role for CPSF6 in the ability of TNPO3-depleted cells to block HIV-1 infection." (PMID 23622145, 2013). "Depletion of TNPO3 expression inhibits HIV-1 infection; however, the simultaneous depletion of TNPO3 and CPSF6 expression rescues HIV-1 infectivity indicating that CPSF6 is required for the ability of TNPO3-depleted cells to block HIV-1 infection." (PMID 23622145, 2013). "High throughput RNA interference (RNAi) screens define a list of NPC components as being necessary host co-factor for HIV-1 infection, including Nup98, Nup85, Nup133, Nup107, Nup160, Nup153, Nup214, Nup358, Nup155, CRM1 (XPO1) and the nuclear import receptor transportin 3 (TNPO3)." (PMID 23959328, 2013). "While TNPO3 may serve more than one role during HIV-1 infection, altered CPSF6 localization seems to account for a major part of the infectivity defect induced by TNPO3 knockdown." (PMID 24103892, 2013). "It is suggested that the reduction of HIV-1 infection upon TNOP3 depletion seemed to be an indirect consequence of the cytoplasmic accumulation of CPSF6, which is restrictive for infection, and therefore the role of TNPO3 in integration site selection remains to be answered." (PMID 36423112, 2022). "Further evidence for a link between CPSF6 and TNPO3 include data showing that mutants of TNPO3 that are selectively impaired for interaction with CPSF6 do not support HIV-1 infection, whilst TNPO3-depleted cells are refractory to wild-type HIV-1 infection only in the presence of endogenous CPSF6." (PMID 25356722, 2014). "While cyclosporine treatment can partially rescue WT HIV-1 infection in TNPO3 depleted cells, the lack of complete rescue may reflect its multiple potential roles in promoting HIV-1 infection." (PMID 24103892, 2013).
gastric cancer (9 papers, 2021 to 2025). A primary or metastatic malignant neoplasm involving the stomach. "For instance, circ-TNPO3 functions as a protein decoy for the insulin-like growth factor 2 mRNA binding protein 3 (IGF2BP3) to inhibit the capacity of gastric cancer cells to proliferate." (PMID 38003674, 2023). "The abnormal expression of TNPO3 circular RNAs (circ-RNAs) can result in ovarian cancer and gastric cancer; therefore, circ-TNPO3 has the potential to serve as a therapeutic target for cancers." (PMID 35456945, 2022). "Thus, circ-TNPO3 played an inhibitory role in the proliferation and metastasis of gastric cancer (GC)." (PMID 36387211, 2022). "Interestingly, we previously reported that circ‐TNPO3 suppressed migration by serving as a protein decoy in gastric cancer." (PMID 35876041, 2022). "For instance, circ-TNPO3 inhibits gastric cancer (GC) metastasis by decoying insulin-like growth factor 2 binding protein 3 (IGF2BP3) protein." (PMID 36380816, 2023). "Circ-TNPO3 can act as a protein decoy for IGF2BP3, weakening the role of IGF2BP3 in stabilizing MYC mRNA, thereby inhibiting gastric cancer cell migration and proliferation." (PMID 37298373, 2023). "Circ-hHBB3 binds HuR and degrades HuR, whereas Circ-TNPO3 competitively binds IGF2BP3 and inhibits the proliferation and metastasis of gastric cancer by regulating the MYC-SNAIL axis, which leads to malignant progression of GC." (PMID 35116058, 2021). "The expression of MYC proto-oncogene, as well as bHLH transcription factor (MYC) and its target, snail family transcriptional repressor 1 (SNAI1), is inhibited when circ-TNPO3 sequesters IGF2BP3, which reduces the ability of gastric cancer cells to proliferate and metastasize." (PMID 38003674, 2023). "Moreover, circRNAs such as circ-transportin 3 (TNPO3) and circular nuclear factor of activated T cells 3 (circNFATC3) interacted with IGF2BP3 protein and further regulated its expression in gastric cancer." (PMID 39856555, 2025). "For example, circ-TNPO3 can interact with IGF2BP3 to weaken the role of IGF2BP3 in stabilizing MYC mRNA, thereby regulating the MYC-SNAIL axis and inhibiting the proliferation and metastasis of gastric cancer (GC)." (PMID 36139074, 2022).
muscular dystrophies (6 papers, 2013 to 2025). "Transportinopathy is a dominantly transmitted LGMD entity due to the involvement of transportin-3, which results in a muscular dystrophy due to a mutation of this nuclear-import protein, which is also known to be involved in HIV virus transport." (PMID 40757538, 2023). "In the context of TNPO3-related muscular dystrophies, such as LGMDD2, and in DM1, previous studies have shown altered levels of miR-206 and miR-1 in patient sera and muscle tissues." (PMID 41291251, 2025). "In particular, we performed a custom enrichment of exons of genes involved in muscular dystrophies, including TNPO3." (PMID 23667635, 2013).